HYAL1 (hyaluronidase 1)
Diseases named in the same sentence as HYAL1 in open-access papers (continued):
Sharing a sentence is not in itself a finding about the gene and the disease.
bladder cancer (14 papers, 2006 to 2025). "For bladder cancer, meta-analyses support the combination of HYAL1 and SURVIVIN as effective urinary diagnostic biomarkers." (PMID 41421148, 2025). "HYAL-1 might be a diagnostic indicator of epithelial ovarian malignancies, as well as bladder cancer, through elevated levels in the serum." (PMID 36613567, 2022). "In male genitourinary cancers such as bladder cancer and aggressive tumors like laryngeal carcinoma, HYAL1 has been demonstrated to actively participate in tumor progression." (PMID 41421148, 2025). "Increased HYAL1 expression correlates with bladder cancer diagnosis and promotes tumor invasion and metastasis, constituting a potential prognostic indicator for progression and recurrence." (PMID 33809973, 2021). "Urine and tissue HAase/HYAL-1 levels are sensitive markers for high-grade bladder cancer (BCa) and its metastasis." (PMID 27419371, 2017). "Increased HYAL1 levels were found to correlate with tumor aggressiveness and poor survival in head and neck, prostate and bladder cancer, whereas HYAL1 expression was decreased in advanced ovarian carcinomas and in endometrial cancer." (PMID 27764788, 2016). "Recently, several genes have been identified that are associated with bladder cancer progression and poor prognosis, such as excision repair cross-complementing group 1 (ERCC1), matrix metalloproteinase-7 (MMP-7), hyaluronidase 1 (Hyal-1)." (PMID 24223213, 2013). "It has been shown that HYAL-1 is present in the culture medium of prostate and bladder cancer cell lines as well as in the urine of patients with bladder cancer." (PMID 21695196, 2011). "A role for Egr-1 in human bladder cancer progression would be expected from the fact that Egr-1 regulates heparanase and HYAL-1 hyaluronidase expression in human bladder cancer cells." (PMID 19878561, 2009). "Moreover, combined use of HAS2 and HYAL-1 hyaluronidase was able to predict bladder cancer diagnosis and prognosis." (PMID 32862195, 2021). "Also the HYAL-1 hyaluronidase expression in bladder cancer has been suggested to be regulated by binding of Egr-1 to the methylated promoter of HYAL-1 hyaluronidase." (PMID 19878561, 2009). "Furthermore, a possible antitumor effect of sHA has also been studied in pre-clinical models of bladder cancer, where sHA fragments significantly attenuate the proliferation, migration and invasion of HYAL1-expressing cancer cells, while also inhibiting angiogenesis." (PMID 33809973, 2021). "Also, both HAS, HYAL1, CD44 and RHAMM were found to be overexpressed in bladder cancer tissues." (PMID 29207682, 2017).
ovarian carcinoma (8 papers, 2009 to 2025). A malignant neoplasm originating from the surface ovarian epithelium. "Our findings in endometrial and ovarian cancer are in contrast to reports on prostate and bladder tumors in which increased HYAL1 protein and mRNA expression is associated with advanced disease and unfavorable prognosis." (PMID 20875124, 2010). "Elevated Hyal1 expression has been observed in several cancers, such as prostate, breast and ovarian carcinomas." (PMID 41465475, 2025). "Our previous results have demonstrated an inverse correlation between HYAL1 and ERα expression in epithelial ovarian cancer cells, suggesting an estrogenic regulation of the HYAL1 gene in ERα positive cancer cells." (PMID 27764788, 2016). "We reported a similar inverse correlation for epithelial ovarian cancers in which clear cell and mucinous subtypes showed strong expression of HYAL1 but low levels of ERα." (PMID 27764788, 2016). "Results from the present work demonstrate that ovarian cancer cell lines expressing high HYAL-1 levels, e.g. derived from clear cell and mucinous EOCs, have low mRNA expression of ERα, ERβ and PR." (PMID 21695196, 2011). "In the past, the expression of Hyaluronidase-1 in ovarian cancer has been described specifically in serous tumors, most probably because this is the most frequent EOC subtype." (PMID 21695196, 2011). "We therefore postulate that regulation of HYAL1 expression by ERα participates in ovarian cancer progression." (PMID 21695196, 2011). "In ovarian cancer, allelic imbalance of these three genes (HYAL1, HYAL2 and HYAL3) has been shown in tumor and stroma tissues." (PMID 21695196, 2011). "More importantly, we determined that HYAL1 mRNA levels are inversely correlated with those of ERα specifically in clear cell and mucinous EOC tissue samples, suggesting a role for ERα in regulating HYAL1 gene expression in ovarian cancer." (PMID 21695196, 2011). "One interesting perspective would be to determine the efficacy and feasibility of a combined test to measure HYAL-1 plasma activity in conjunction with CA125 measurements for ovarian cancer screening." (PMID 21695196, 2011). "In ovarian cancer, allelic imbalance of the HYAL1/2/3 clustered genes was reported in tumor and stroma tissues, and in particular, HYAL1 expression was significantly reduced in serous epithelial ovarian cancer compared to normal ovaries or to other ovarian cancer subtypes." (PMID 27764788, 2016). "In addition, ectopic expression of ERα in TOV21G ovarian cancer cells, which are derived from a clear cell carcinoma, resulted in a significant decrease in HYAL1 expression." (PMID 27764788, 2016). "In the present work we performed a detailed study on the expression of HYAL-1 in ovarian cancer tissue samples representing four different histopathological subtypes and showed elevated levels of this enzyme in clear cell and mucinous EOCs, but not in serous or endometrioid." (PMID 21695196, 2011). "The HYAL1 gene is located in a tumor suppressor locus at chromosome 3p and cytogenetic studies have revealed recurrent anomalies of chromosome 3 in ovarian cancer that include a non-random loss of all or regions of the 3p arm." (PMID 21695196, 2011). "This was the first evidence showing high circulating HYAL-1 levels in ovarian cancer." (PMID 21695196, 2011). "HAS1, HYAL1 and HYAL4 mRNA expression is significantly upregulated, whereas HAS2, HYAL2 and HYAL3 mRNA expression is significantly downregulated in ovarian cancer tissue compared to controls." (PMID 35767191, 2022). "The present findings of decreased HYAL1 and HYAL2 mRNA in endometrial cancer are consistent with the results we have recently shown in ovarian cancer." (PMID 20875124, 2010).
ovarian carcinoma (continued). "Furthermore, HYAL1 transcript levels correlated with hyaluronan content (r = -0.4; P = 0.025) and hyaluronidase activity (r = 0.5; P = 0.006, n = 32), suggesting that HYAL1 dominated the differences in hyaluronidase activity and contributed to the accumulation of hyaluronan in the ovarian cancers." (PMID 19435493, 2009). "Our TNMplot analysis of over 700 ovarian cancer specimens revealed that HAS1, HYAL1 and HYAL4 mRNA expression is significantly upregulated, whereas HAS2, HYAL2 and HYAL3 mRNA expression is significantly downregulated in ovarian cancer tissue compared to controls." (PMID 35767191, 2022). "Our results show that HYAL-1 is also secreted by the ovarian cancer cell line originating from the clear cell carcinoma, but not from that of serous EOC." (PMID 21695196, 2011). "HYAL1 and HYAL2 expression was not different between the chemosensitive and chemoresistant primary ovarian cancer cells nor between CBP-resistant OV-90 cells compared to parental cells." (PMID 31443261, 2019).
colorectal cancer (7 papers, 2020 to 2025). A primary or metastatic malignant neoplasm that affects the colon or rectum. "•Biomarker and Diagnostic Value: HYAL1 serves as a prognostic biomarker in multiple cancers (e.g., bladder, oral, and colorectal cancer) and is detectable in serum and urine, supporting its clinical utility." (PMID 41421148, 2025). "HYAL1 inhibited colorectal cancer metastasis via the regulation of TIMPs/MMPs balance, further suppressing migration and invasion of colon cancer cells." (PMID 37689745, 2023). "•Dual-Functionality of HYAL1: HYAL1 exhibits paradoxical roles in cancer, acting as both a tumor promoter (e.g., in prostate, esophageal, and osteosarcoma) and a tumor suppressor (e.g., in colorectal cancer), highlighting its context-dependent nature." (PMID 41421148, 2025). "In colorectal cancer, high expression of HYAL1 and HYAL2 can inhibit tumor metastasis, but in triple-negative breast cancer, high expression of HYAL2 genes is associated with shorter disease-free survival, higher tumor recurrence rate, and higher tumor metastasis rate." (PMID 33381460, 2020). "However, we found a decrease in Hyaluronidase 1 HYAL1 levels in the breast but not colorectal cancer." (PMID 32610620, 2020).
lung carcinoma (7 papers, 2007 to 2025). "It is noteworthy that the 3p21.3 region is considered a potential tumor suppressor gene (TSG) locus, and HYAL1 shares sequence identity with the previously reported LuCa-1 (lung cancer 1), which frequently exhibits loss of heterozygosity or homozygous deletion in most lung cancers." (PMID 41421148, 2025). "For lung cancer, all manuscript-referenced genes were captured by either SHAP or LIME, with notable overlaps such as MYBL2, HYAL1, CLIC5, ADGRF5, and CLDN18." (PMID 40565055, 2025). "The correlation coefficient according to Spearmen's rank test between HYAL1 and HYAL2 mRNA level was 0.67 (P = 0.005) in lung cancer samples (i.e statistically valid)." (PMID 18725949, 2008). "Our observation of reduced HYAL1 expression in IPF lung tissue was consistent with reports of the absence of HYAL1 mRNA in lung carcinoma cell lines and reduced HYAL1 protein levels in endometrial carcinomas." (PMID 32258117, 2020). "Since we demonstrated tumour suppressor function of HYAL1 and HYAL2 in SCID mice, we suggested that in primary renal and lung cancers expression of these genes might also be distorted." (PMID 18725949, 2008). "Expression of HYAL1 and HYAL2 was almost undetectable in the KRC/Y renal and U2020 lung carcinoma lines (data not shown), which were used in our growth suppression experiments for testing RASSF1A and G21/NPRL2." (PMID 18725949, 2008).
colon cancer (6 papers, 2020 to 2025). "For instance, in colon cancer models, HYAL1 overexpression surprisingly suppressed tumor formation, suggesting potential tumor-suppressive capabilities." (PMID 41421148, 2025). "In vitro studies have also demonstrated the contribution of HYAL-1 in tumour cell proliferation, motility, invasion, tumour growth, metastasis, and angiogenesis in breast, bladder, prostate, and colon cancer." (PMID 38256245, 2024). "The activity of multiple hyaluronidase isoforms (HYAL1, 2, 3, and SPAM1) is increased in colon cancer patients, and the increased HYAL1 and HYAL2 are particularly closely related to the aggressiveness of cancer." (PMID 37568202, 2023). "In xenograft models of breast, bladder, and colon cancer, HYAL-1 has proved to promote tumor mobility and penetration." (PMID 36613567, 2022). "For instance, HYAL1 overexpression was shown to suppress tumorigenicity in a colon cancer model." (PMID 41421148, 2025). "For example, overexpression of HYAL-1 inhibited carcinogenesis in rat colon cancer cells." (PMID 36613567, 2022).
endometrial cancer (5 papers, 2010 to 2021). Primary or metastatic malignant neoplasm involving the endometrium (mucous membrane that lines the endometrial cavity). "For example, in endometrial cancer, HYAL1 and HYAL2 are downregulated compared to healthy tissue, and this phenotype correlates with the accumulation of hyaluronan." (PMID 34540372, 2021). "The role of HYAL1 as a tumor suppressor or oncogene remains unclear with reports of both HYAL1 downregulation in human endometrial cancer and lung and kidney carcinomas and upregulation in breast, epithelial ovarian, and bladder tumors." (PMID 32258117, 2020). "It is possible that in endometrial cancer the HYAL mRNA expression depends on the status of the chromosome 3p21.3 locus, and the decreased expression of HYAL1 and HYAL2 may be explained by concomitant deletions of these closely mapped genes." (PMID 20875124, 2010).
head and neck squamous cell carcinoma (5 papers, 2008 to 2025). A squamous cell carcinoma that arises from any of the following anatomic sites: lip and oral cavity, nasal cavity, paranasal sinuses, pharynx, larynx, and salivary glands. "Interestingly, the gene encoding HYAL1 maps to chromosome 3p21.2-p21.3, a conserved candidate tumor suppressor locus, is inactivated in head and neck squamous cell carcinomas." (PMID 24244714, 2013). "Nevertheless it was reported that HYAL1 was inactivated in six of seven head and neck squamous cell carcinoma lines by illegitimate splicing." (PMID 18725949, 2008). "For head and neck squamous cell carcinoma (HNSCC), HYAL1 demonstrates potential as a tissue-specific biomarker, with elevated HYAL1 and PH20 expression observed in laryngeal carcinoma specimens." (PMID 40646377, 2025). "We have previously demonstrated that in head and neck squamous cell carcinoma (HNSCC) ΔNp63 controls the expression of the HA-related genes HAS3, HYAL1, and CD4446." (PMID 30139970, 2018).
Diabetes (4 papers, 2022 to 2026). "Elevated levels of HYAL1 and HA have also been reported in systemic diseases such as severe dengue and diabetes where glycocalyx degradation, vascular instability, and hyperpermeability effects have been associated." (PMID 35164755, 2022). "Diabetes upregulated Hyal-1, CD44, RHAMM and reactive oxygen species in rat retinas." (PMID 41789111, 2026).
mucopolysaccharidosis type IX (4 papers, 2020 to 2025). "Due to its exceptionally high metabolic turnover rate in vivo, dysregulation of HA metabolism can lead to severe pathological conditions, such as mucopolysaccharidosis type IX (MPS IX) resulting from hyaluronidase 1 (HYAL1) deficiency." (PMID 41421148, 2025). "Major clinical developmental phenotypes result from mutations in hyaluronidases such as mucopolysaccharidosis type IX from Hyal1, bone defects, and cardiopulmonary dysfunction from loss of Hyal2." (PMID 31914398, 2020). "In the case of mucopolysaccharidosis type IX, it is caused by the deficiency of HYAL1." (PMID 38396603, 2024). "Mucopolysaccharidosis type IX (MPS IX) is caused by homozygous or compound heterozygous variants in the gene HYAL1, which encodes the enzyme hyaluronidase-1." (PMID 41154677, 2025).
pancreatic cancer (4 papers, 2013 to 2023). "We demonstrate, for the first time, that expression patterns of HA and its regulators (HAS2 and HYAL1) are significantly associated with survival of patients with pancreatic cancer." (PMID 24244714, 2013). "Reports substantiate high expressions of endogenous HYAL2 and HYAL3 in different pancreatic cancer cell lines including the Panc-1, and a negligibly low level of HYAL1." (PMID 33572222, 2021). "Knockdown of HYAL1 in pancreatic cancer cells significantly decreases pancreatic cancer cell migration in the presence of high molecular weight HA (HMW-HA), indicating a HYAL1-dependent mechanism by which the newly formed LMW-HA derivatives promote motility." (PMID 33809973, 2021). "Our present results raise a possibility of tumor-suppressor role of HYAL1 in pancreatic cancer, but further studies are required to validate its functional relevance." (PMID 24244714, 2013). "The present study demonstrated significant correlations between increased expressions of HA and HAS2, and decreased expression of HYAL1 and poor prognosis in patients with resected pancreatic cancer." (PMID 24244714, 2013). "Together, our results demonstrate the pro-tumorigenic role of HYAL1 in pancreatic cancer and identify the role of BRD2 in the regulation of HYAL1 in PDAC." (PMID 37296612, 2023). "Unlike HA and HAS2, decreased expression of HYAL1 correlated with poor survival in our present series of pancreatic cancer." (PMID 24244714, 2013).
colitis (3 papers, 2021 to 2024). Inflammation of the colon. "Since prior studies had shown skin wounding (and K14/HYAL1 mice) resulted in increased susceptibility to colitis to DSS, we next sought to determine if the alterations in the intestinal microbiome might explain this phenomenon." (PMID 38589392, 2024). "Moreover, the DNBS challenge caused a massive increase in HYAL-1 expression on the 3rd day (152% *** p < 0.001 vs. DNBS group), and such an effect was still preserved on the 7th day after colitis induction (+172% *** p < 0.001 vs. DNBS group)." (PMID 38203336, 2023). "Consistently with the data obtained in murine colitis, Ade/HA determined a significant decrease in the release of IL-1β, TNF-α, IL-6, MPO, and MDA accumulation in cytomix-stimulated tissues, and these effects were accompanied by a significant reduction in the expression of HYAL-1." (PMID 38203336, 2023).
idiopathic pulmonary fibrosis (3 papers, 2017 to 2021). Idiopathic pulmonary fibrosis (IPF) is a nonneoplastic pulmonary disease that is characterized by the formation of scar tissue within the lungs in the absence of any known cause. "We have studied the conjugate of Pluronic L31 and hyaluronidase 1 as a potential therapeutic agent for the treatment of pulmonary fibrosis." (PMID 34070506, 2021). "Therefore, HYAL1 could potentially affect the pathogenesis of lung fibrosis through counteracting HASs." (PMID 32258117, 2020). "HYAL1 was one of the top 25 genes that was significantly downregulated in IPF lung tissues, which supports the reported antifibrotic effect of hyaluronidases in lung fibrosis." (PMID 32258117, 2020). "Furthermore, we also found that LPS‐induced expressions of extracellular matrix genes such as TNC and HYAL1, as well as a vasopressor gene, EDN1, all of which are involved in the process of lung fibrosis, were also dose dependently downregulated by antofine treatment." (PMID 28805975, 2017).
kidney cancer (3 papers, 2008 to 2020). Primary or metastatic malignant neoplasm involving the kidney. "Our findings are also similar to those of lung and kidney cancer samples in which a major down-regulation of HYAL1 and HYAL2 genes has been shown." (PMID 20875124, 2010). "In contrast, recent findings have shown that the expression of HYAL1 and HYAL2 genes is significantly decreased in lung and kidney cancer samples." (PMID 20875124, 2010).
melanoma (3 papers, 2012 to 2025). A malignant, usually aggressive tumor composed of atypical, neoplastic melanocytes. "Transwell migration assays showed that down-regulating Hyal1, Tspan10, and Mc1r resulted in clearly reduced migration of the melanoma cells." (PMID 22363655, 2012).
osteoarthritis (3 papers, 2013 to 2022). A noninflammatory degenerative joint disease occurring chiefly in older persons, characterized by degeneration of the articular cartilage, hypertrophy of bone at the margins and changes in the synovial membrane. "This disease causes juvenile arthritis in humans and osteoarthritis in the Hyal1 knockout mouse model." (PMID 35710820, 2022). "Of note, the classical “Osteoarthritis Pathway” was the top signaling pathway affected by HYAL1 overexpression." (PMID 32258117, 2020).
ovarian tumor (3 papers, 2011 to 2022). "Consistent with such HYAL1 reduction, extracellular accumulation of hyaluronan is often observed in ovarian tumor stroma and pericellular matrix with correlation to poor disease outcome." (PMID 27764788, 2016). "We further went on to verify whether expression of Hyaluronidase-1 inversely correlated with that of ERα, ERβ and/or PR in ovarian tumor samples." (PMID 21695196, 2011). "However, to our knowledge this is the first demonstration of a correlation between HYAL1 and ERα mRNA levels in ovarian tumor cells and more importantly in tumor samples collected from patients." (PMID 21695196, 2011). "We have also reported such negative relationship in ovarian tumors, in which poor prognosis morphological subtypes, such as clear cell and mucinous tumors, exhibit high HYAL1 expression levels that are inversely correlated with ERα expression." (PMID 27764788, 2016).